CD4 (CD4 molecule)
Diseases named in the same sentence as CD4 in open-access papers (continued):
Sharing a sentence is not in itself a finding about the gene and the disease.
pulmonary fibrosis (continued). "IL-6 has also been proposed to cause lung fibrosis, it skews the inflammation towards Th17 type and also results in suppression of Th1 response and differentiation of CD4+ cells into a profibrotic Th2 type which promotes lung fibrosis." (PMID 36106257, 2022). "Lung fibrosis is characterized by a Th2 immune response with increased CD4+ T-cells and the CD4+/CD8+ ratio." (PMID 35346317, 2022). "Our study suggests that the effects of an AhR ligand, FICZ, on AhR led to increase the number of Tregs and reduced that of CD4+IFNγ+ T cells and contributed to alleviating lung fibrosis." (PMID 32033616, 2020). "Meanwhile, fibroblasts and CD4+ T lymphocytes in IPF have been shown to express PD‐L1 and PD‐1, respectively;38, 39 the upregulation of both is associated with pulmonary fibrosis." (PMID 32986306, 2020). "These granulomas are associated with inflammation in the broncho‐alveolar spaces, expansion of the draining lymph nodes and CD4+ T‐cell activation which in turn can lead to pulmonary fibrosis." (PMID 32742653, 2020). "Instead, depletion of CD4+ T cells during the pneumonitic phase decreased radiation-induced lung fibrosis in rats pointing to a contribution of CD4+ T cells to disease pathogenesis." (PMID 31024543, 2019). "We further tested the expression of 4-1BB in CD4+ T cells (including effector and naïve T cells), which are involved in CS-induced inflammation and pulmonary fibrosis." (PMID 30250465, 2018). "Our findings are consistent with the suppression of CXCL-9 by IL-22 in an animal model of lung fibrosis which limited recruitment of CD4+CXCR3+ T cells and attenuation of lung inflammation and fibrosis." (PMID 29163483, 2017). "In that study, IL-22 protects against lung fibrosis by suppressing the CXCL9-dependent recruitment of CD4+ T cells into the lung." (PMID 27650379, 2016). "CD4+ Th1 and Th2 cells and their cytokines appear crucial to the pathogenesis of pulmonary fibrosis." (PMID 25944985, 2015). "Of note, depletion of CD4+ T cells during the pneumonitic phase decreased radiation-induced lung fibrosis pointing to a contribution of these cells to disease pathogenesis." (PMID 24766907, 2014). "Recent results also indicated that regulatory T cells CD4+ Foxp3+ (T regs) accumulated during the development of pulmonary fibrosis, possess a strong fibrotic activity in mice treated with silica." (PMID 25050810, 2014). "In silica-exposed animals depleted of T regs, pulmonary fibrosis occurred, but increased numbers of CD4+ T effectors were present." (PMID 22824096, 2012). "In general, it appears that although both CD4+ and CD8+ T cells are associated with pulmonary fibrosis, CD8+ T cells appear to be associated with a worse prognosis." (PMID 22824096, 2012). "We next sought about the mechanisms of CD4+CD25+Foxp3+ regulatory T cells in silica-induced lung fibrosis." (PMID 21072213, 2010). "Secondly, we want to investigate the regulatory role of CD4+CD25+Foxp3+ Treg cells in silica-induced lung fibrosis by studying the mRNA expression of typical Th1 (IL-2, IFN-γ) and Th2 (IL-4) cytokines." (PMID 21072213, 2010). "To determine the mechanism of Treg cells in silica-induced lung fibrosis, we first examined the effective fraction (CD4+CD25+Foxp3+ Treg cells) in HLN, spleen and BALF." (PMID 21072213, 2010). "Participation of CD4+ T cells, including Th1 and Th2 cells, in the pathogenesis of lung fibrosis induced by silica particles has been indicated in several studies." (PMID 21072213, 2010). "To investigate the role of CD4+CD25+Foxp3+ regulatory T cells in silica-induced lung fibrosis, we first assessed the population of CD4+CD25+Foxp3+ T cells in HLN, spleen and BALF." (PMID 21072213, 2010). "Depletion of CD4+CD25+Foxp3+ regulatory T cells enhanced Th1 response at the later stage of lung fibrosis." (PMID 21072213, 2010). "These suggested that CD4+CD25+Foxp3+ regulatory T cells played a regulatory role in silica-induced lung fibrosis by modulating Th1/Th2 balance." (PMID 21072213, 2010).
pulmonary fibrosis (continued). "To test the potential suppression of silica-induced lung fibrosis in mice by endogenous CD4+CD25+ Treg cells, we generated CD25+ T cell-depleted C57BL/6 mice by injection of the anti-CD25 mAb PC61." (PMID 21072213, 2010). "The regulatory function of CD4+CD25+Foxp3+ Treg cells in silica-induced lung fibrosis depends on direct mechanism at the inflammatory stage and indirect mechanism during the fibrotic stage in silica-induced lung fibrosis." (PMID 21072213, 2010). "Furthermore, in idiopathic pulmonary fibrosis cases, elevated CD4/CD8 ratios in BALF correlate with accelerated functional decline, 33 suggesting mechanisms across fibrotic lung diseases." (PMID 41494735, 2026). "It has been demonstrated that upregulating PD-1 gene expression in CD4+T cells from IPF patients can promote the process of lung fibrosis, and experiments carried out in mice have shown that up-regulation of the PD-1 gene promotes the process of silicosis fibrosis." (PMID 40433386, 2025). "And blocking the Wnt/β-catenin signaling pathway by direct oral-bronchial injection of β-catenin shRNA in silicosis mice could alter the CD4+T subpopulation and could alleviate the process of silica-induced lung fibrosis." (PMID 40433386, 2025). "However, the study of DCs in pulmonary fibrosis has been overlooked due to publication of seminal work demonstrating that CD4+ and CD8+ lymphocytes, and by extension the DCs that prime those responses, are not important in mediating fibrotic effects." (PMID 39964756, 2025). "An increase in CD4+T cells in the peripheral blood of patients with idiopathic pulmonary fibrosis (IPF) may promote macrophage infiltration in the pulmonary bronchi and their subsequent polarization into the M1 phenotype." (PMID 40433386, 2025). "The violin plot of the immune cell infiltration difference demonstrated that patients with idiopathic pulmonary fibrosis had a higher level of B cells memory, Plasma cells, T cells CD4 naive, Macrophages M0, Macrophages M2 and Mast cells resting compared with the control group." (PMID 39935693, 2024). "In addition, and similarly to lung fibrosis, the peripheral blood of RA patients contains enlargement of both memory and CD4+CD28− T cell populations." (PMID 39062798, 2024). "Interestingly, the reduced expression of α-Klotho, known for its anti-aging and anti-inflammatory properties, in peripheral blood CD4+ cells suggests premature aging potentially linked to decreased CD28 expression, akin to observations in pulmonary fibrosis." (PMID 39062798, 2024). "We demonstrated that IL-7 neutralization in the lung was effective in alleviating CS-induced pulmonary fibrosis by decreasing pathogenic CD4+ TRM-Teff cells but not TRM-Tregs expressing low IL-7R." (PMID 39122899, 2024). "Because transcription factor ESR-1 (alpha subunit of ESR) was identified as binding to the STAT3 gene in CD4+ T cells, we investigated the role of the ERα subunit in profibrotic cytokine expression using a murine model of bleomycin-induced lung fibrosis in WT and ESR-1 knockout (ESR-1-/-) mice." (PMID 36899902, 2023). "IL-25 can also promote the infiltration of eosinophils and CD4+ T cells into the airways and skin by promoting a type 2 cytokine response, which may even induce pulmonary fibrosis during allergic inflammation." (PMID 37005677, 2023). "However, the immunologic consequences of ERα binding to the STAT3 gene in CD4+ T cells of patients with lung fibrosis remain unexplored." (PMID 36899902, 2023). "Our clinical data were further corroborated by experimental evidence showing similar expression patterns in the bleomycin model of lung fibrosis including increased PD-1, PD-L1 mRNA levels and CD4/CD8 ratio in tracheobronchial lymph nodes compared to saline-treated mice." (PMID 37964265, 2023).
pulmonary fibrosis (continued). "Because of the role of female gonadotrophic hormones in reducing the CD4+ T cell-mediated proinflammatory and profibrotic environment in mouse models of lung fibrosis, we probed samples from human patients with fibrotic lung diseases for sex-associated differences." (PMID 36899902, 2023). "Therefore, we analyzed the proportion of IL-17-producing CD4+ T-cells and TGF-β-producing CD4+ T-cells in a single-cell suspension derived from lung tissue of a mouse model of BLM-induced lung fibrosis." (PMID 36301948, 2022). "Interestingly, the two patients with pulmonary fibrosis showed the lowest CD3+CD4+ and CD3+CD8+ T cells count at admission time." (PMID 33182268, 2020). "There has been a discussion whether inflammation is involved in the process of fibrosis, especially in IPF, but CD4+ helper T cells, especially the shift to Th2, are also thought to be important for the patients with idiopathic pulmonary fibrosis." (PMID 32033616, 2020). "The authors concluded that a therapeutic strategy of expanding CD4+CD25highFoxP3+ in humans may be harmful via the augmentation of Th2 immune responses in patients with idiopathic pulmonary fibrosis and other fibroproliferative lung diseases." (PMID 30374354, 2018). "Furthermore, depletion of CD4+ T cells during the pneumonitic phase attenuated the development of lung fibrosis upon thoracic irradiation in a murine model." (PMID 28018357, 2016). "Furthermore, it has been confirmed that bvPLA2 induced Tregs from naïve CD4 positive T cells and that Tregs are critical to lung fibrosis." (PMID 27144583, 2016). "The role of CD4+ T cells in fibrosis has been elucidated in a drug-induced lung fibrosis model." (PMID 26176698, 2015). "In the previously reported mouse model of hypersensitivity pneumonitis, the authors found that IL-22-secreting γδT cells could protect from lung fibrosis by diminishing recruitment of CD4+T cells to the lung." (PMID 23476100, 2013). "Altogether, our study showed that depletion of CD4+CD25+ regulatory T cells decelerated the progress of silica-induced lung fibrosis and this might provide a new insight in limit the process of fibrosis for silicosis patients by using anti-CD25 Abs." (PMID 21072213, 2010). "Additionally, along with these exhaustion markers indicating decreased immunofitness in lung fibrosis, there is evidence that accelerated senescence in CD4+ T cells might play a role." (PMID 39062798, 2024). "Together, our data suggest that PARP inhibition may accelerate the resolution of TB lung disease when used in combination with effective antibiotics by reducing neutrophil recruitment, CD4+ T cell responses, and lung fibrosis, thus antagonizing granuloma formation or maintenance." (PMID 38071218, 2023). "PD-1 + CD4 + cells could represent potential therapeutic targets for lung fibrosis." (PMID 37964265, 2023). "Therefore, the induction of differentiation of naïve CD4+ T cells into IL-17+ CD4+ T cells by Ly6c+ MoMs may be a potential mechanism for pulmonary fibrosis." (PMID 36870972, 2023). "CD4 T cells may regulate pulmonary fibrosis in multiple ways." (PMID 36578501, 2022). "In addition, WBC, neutrophils, and CD4/CD8 were correlated with pulmonary fibrosis and HRV." (PMID 35126184, 2021). "Thus, IL-17 may be another contributor among the CD4+ T lymphocyte subsets to more end-organ severe glomerular mesangial expansion and pulmonary interstitial fibrosis in sNASP mutant mice." (PMID 34720750, 2021). "Our research corroborates and extends these findings by demonstrating an increase in CD4+PD-1+ T cells both in patients with SSc-ILD and a mouse model of BLM-induced pulmonary fibrosis." (PMID 41494735, 2026). "Beyond their roles in immune homeostasis, the interplay between CD4+T cells, CD8+T cells, and macrophages in the lungs is central to alveolar regeneration and the development of pulmonary fibrosis." (PMID 40433386, 2025).
pulmonary fibrosis (continued). "On the contrary, experiments in mice and samples from humans showed that lung CCR2+CD4+T cells have an immunosuppressive effect and can reduce BLM-induced lung inflammation and lung fibrosis." (PMID 40433386, 2025). "Counterintuitive findings from another study showed that exogenous administration of the AHR ligand FICZ ameliorated pulmonary fibrosis, presumably by augmenting numbers of FoxP3+ Tregs and decreasing IFN-γ+ CD4+ and IL-17A+ γδ+ T cells." (PMID 39964756, 2025). "This review focuses on the role of CD4+T cell and CD8+T cell subsets in pulmonary inflammation and fibrosis, investigating their potential as therapeutic targets for managing pulmonary fibrosis." (PMID 40433386, 2025). "All three chemokines are ligands for CXCR3, recruit CD4+ Th1 cells and CD8+ T cells to the site of tissue injury, and inhibit angiogenesis during pulmonary fibrosis." (PMID 37493737, 2023). "In this review, we have summarized the role of CD4+ T cells and AEC apoptosis which is a prominent observation in lung biopsies of patients with idiopathic pulmonary fibrosis (IPF)." (PMID 37063828, 2023). "CD8+ and CD4+ T-cells play a key role in BLM-induced fibrosis, because a reduction of individual T-cell subsets attenuates lung fibrosis, and fibrosis is completely prevented by simultaneous depletion of both T-cell subsets." (PMID 37373275, 2023). "Alveolar macrophages and CD4+ T cells secrete CCL1, which promotes the differentiation of lung fibroblasts into myofibroblasts and contributes to pulmonary fibrosis." (PMID 37122736, 2023). "CD4+lymphocytes increased in lung biopsy samples of RA-UIP patients, as well as Th17 cells participated in pulmonary fibrosis by release of IL-17A and TGF-β promoting the proliferation of fibroblasts and the formation of extracellular matrix." (PMID 37563706, 2023). "CD4(+) T cells have been reported to exert an anti-fibrotic effect throughout IFN-γ secretion in experimental models of kidney and pulmonary fibrosis." (PMID 36232442, 2022). "IFNγ+CD4+ T cells in the lungs and IFNγ in bronchoalveolar lavage fluid are increased following intratracheal administration of BLM, culminating in lung fibrosis." (PMID 32033616, 2020). "Data presented demonstrate that pulmonary CFPs from silica-induced pulmonary fibrosis exhibit an inhibitory role toward the Th1 phenotype based on decreased production of IL-2 and IFN-γ by CD4+ and CD8+ T cells." (PMID 28700752, 2017). "From the patient history, two patients were monitored for pulmonary fibrosis and two patients had HIV-positive serology with a CD4 count <50." (PMID 28787454, 2017). "Antibody-mediated inhibition of the accumulation of CD3+ lymphocytes or depletion of CD4 and CD8 T lymphocytes also reduced fibrosis levels in the murine model of pulmonary fibrosis induced by the radiomimetic and DNA-damaging drug bleomycin (BLM)." (PMID 28018357, 2016). "Depletion of CD4+CD25+Foxp3+ regulatory T cells limited and delayed the Th2 responses in silica-induced lung fibrosis." (PMID 21072213, 2010). "And in our study, depletion of CD4+CD25+Foxp3+ regulatory T cells indeed limited and delayed the Th2 responses in silica-induced lung fibrosis." (PMID 21072213, 2010). "Depletion of CD4+CD25+Foxp3+ Treg cells enhanced Th1 response and decelerated Th1/Th2 balance toward a Th2 phenotype in silica-induced lung fibrosis." (PMID 21072213, 2010). "We further substantiated this hypothesis in vitro by directly inducing fibroblast differentiation using CD4+PD-1+ T cells, likely through TGF-β1 and IL-17A overproduction, as demonstrated in our observations of BLM-induced pulmonary fibrosis in murine models." (PMID 41494735, 2026). "The identified associations of increasing pulmonary CD8 + lymphocytes, and decreasing CD4/CD8 ratio, each with increasing fibrosis score in mice, are supported by similar correlations reported with lavage lymphocytes of patients with idiopathic pulmonary fibrosis." (PMID 41261392, 2025).
pulmonary fibrosis (continued). "By producing specific CD4+T and CD8+T cell subtypes, the immune system can fine-tune itself to prevent inappropriate activation, but the role of various CD4+T and CD8+T lymphocyte subsets in the progression of pulmonary fibrosis was controversial." (PMID 40433386, 2025). "In this work we demonstrate the different radiation-induced lung responses, of early onset pneumonitis in C3H/HeJ mice, and later onset pneumonitis with pulmonary fibrosis of C57BL/6J mice, to correlate with the CD4/CD8 pulmonary lymphocyte profile of the strains." (PMID 41261392, 2025). "This article summarizes the role of CD4+T cells and CD8+T cells in pulmonary fibrosis." (PMID 40433386, 2025). "The distinctions in the percentages of CD4 + IL-6+ and CD4 + IL-17A + T cells among mice in different housing cohorts support microbiota-induced alterations to the IL-6/ STAT3/IL-17A pathway in pulmonary fibrosis." (PMID 36543914, 2022). "Importantly, lower PD-1 expression on CD4+ T or CD8+ T cells in PB was positively correlated with the percentage of FVC predicted, implying a link between pulmonary fibrosis development and downregulation of the PD-1/PD-Ls pathway." (PMID 34022844, 2021). "Decreased PD-1 expression on CD4+ T or CD8+ T cells in PB was positively correlated with the asbestosis severity, implying that pulmonary fibrosis development in patients with asbestosis was positively correlated with the downregulation of the PD-1/PD-Ls pathway." (PMID 34022844, 2021). "Taken together, we hypothesize that FICZ attenuated lung fibrosis induced by BLM via AhR and at least one of the mechanisms was expanding CD4+ Tregs." (PMID 32033616, 2020). "Taken together, these results demonstrate that CD4+ T-cell activation in the blood and bronchoalveolar space is a feature of patients with FPF, and they provide suggestive evidence that the lung is a site of antigen exposure in pulmonary fibrosis." (PMID 29445374, 2018). "Similar to MCP-1, percentages of CCR2+CD4+ cells were significantly higher in ILD children with pulmonary fibrosis as compared to children with non-fibrotic ILD." (PMID 16095529, 2005). "By contrast, abrogation of the long-lasting (6 months) increase in CD4+CD25+ Treg observed in irradiated lungs of C57BL/6 mice by long-term CD4+CD25+ T cell depletion with an anti-CD25 antibody reduced the increase in fibrocytes and attenuated radiation-induced lung fibrosis." (PMID 28018357, 2016). "In accordance with these observations, we noted that a recruitment of lung CD4+ T lymphocytes, T regs and Th17 cells (IL-17A), but not CD8+ T or NK cells (not shown), was associated with lung fibrosis in WT animals after silica treatment." (PMID 25050810, 2014). "After excluding invariant natural killer T (iNKT) cells to gate conventional T cells, we observed an elevated cell ratio and number of lung CD4 T cells, but not CD8 T cells in mice with pulmonary fibrosis." (PMID 38789926, 2024). "Notably, CD4+ T cells in cluster T9 expressed high levels of KLF6 that positively regulates the expression of TGFβ and molecules in the TGFβ pathway, AREG (amphiregulin) that is involved in pulmonary fibrosis, and CXCR4 that may promote T-cell migration to the lung." (PMID 35558069, 2022). "There was a significant increase in the percentage of monocyte/macrophages and regulatory (CD4+CD25+) T cells in TGFβ1 TG mice with lung fibrosis compared to WT and TGFβ1 TG mice without lung fibrosis." (PMID 32210242, 2020).